EZH2 (enhancer of zeste 2 polycomb repressive complex 2 subunit)
Diseases named in the same sentence as EZH2 in open-access papers (continued):
Sharing a sentence is not in itself a finding about the gene and the disease.
osteoporosis (15 papers, 2016 to 2025). A condition of reduced bone mass, with decreased cortical thickness and a decrease in the number and size of the trabeculae of cancellous bone (but normal chemical composition), resulting in increased fracture incidence. "But EZH2 inhibition increases bone density in adult mice and alleviates bone loss in ovariectomy osteoporosis mice model." (PMID 33759287, 2021). "Using lentivirus-expressed shRNA to knock down EZH2 effectively slowed the progression of osteoporosis." (PMID 40299567, 2025). "A recent publication identified the histone methyltransferase enhancer of Zeste homology 2 (EZH2), which regulates the lineage commitment of MSCs and, therefore, contributes to the pathology of osteoporosis." (PMID 33167522, 2020). "Ezh2 maintains the repression of key cell senescence inducer genes through H3K27me3, and deletion of Ezh2 in early pubertal mice results in premature cellular senescence, depleted MSPCs pool, and impaired osteogenesis as well as osteoporosis in later life." (PMID 29101351, 2017). "For the TFBSs, we identified 2 TFBSs (EZH2 and RAD21) for enrichment, and 2 TFBSs (ELK4 and HDAC1) for depletion in the promoters of osteoporosis-associated genes, respectively." (PMID 27465306, 2016). "According to our findings, epigenetic therapy inhibiting the function of EZH2 might be a promising treatment to prevent osteoporosis in the aged population." (PMID 34874118, 2022). "The deletion of Ezh2 in mice during early puberty led to accelerated cellular senescence, a decrease in MSPC cell populations, and impaired osteogenesis as well as osteoporosis." (PMID 41170318, 2025). "In our previous study, we found that enhancer of Zeste Homolog 2 (EZH2), a methyltransferase, was increased in BMSCs during osteoporosis, resulting in the suppression of osteogenic differentiation of BMSCs." (PMID 34874118, 2022). "Further bioinformatic analysis revealed 8 core targets (EGFR, AR, ESR1, MAPK8, MDM2, EZH2, ERBB2 and MAPT) in the VitD-COVID-19-osteoporosis network." (PMID 36307516, 2022). "Except for that, knockdown of Ezh2 gene by lentivirus-expressing shRNA decreases H3K27me3 on Wnt genes, reversing the abnormal MSC adipogenic lineage commitment in osteoporosis." (PMID 32963550, 2020). "He knocked out Ezh2f/f in Nestin‐creER and found that deletion of Ezh2 (Ezh2−/−) in early pubertal mice resulted in premature cellular senescence, depleted the MSPC pool, and impaired osteogenesis and osteoporosis in later life." (PMID 29488314, 2018). "For instance, in osteoporosis, the upregulated EZH2 and KDM5A and downregulated absent, small, or homeotic 1-like (ASH1L) genes suppress Wnt and Runx2 pathways by altering H3K4me3 and H3K27me3 levels." (PMID 32963550, 2020). "The long‐term inhibition of EZH2 does not appear to be beneficial in adolescent or young adult osteoporosis mice model; short‐term or local applications using EZH2 inhibitor in mature or engineered skeletal tissue may accelerate the maturation of differentiated osteoblasts." (PMID 33759287, 2021).
pancreatic ductal adenocarcinoma (15 papers, 2016 to 2025). An infiltrating adenocarcinoma that arises from the epithelial cells of the pancreas. "EZH2 is overexpressed in many cancers, and studies in mice attributed both prooncogenic and tumor suppressive functions to EZH2 in pancreatic ductal adenocarcinoma (PDAC)." (PMID 39739419, 2024). "Collectively, our data revealed SOX8/EZH2/SPARC signaling induced primary chemo-resistance of albumin-bound paclitaxel in pancreatic ductal adenocarcinoma." (PMID 35173526, 2022). "In pancreatic ductal adenocarcinoma, EZH2 silences GATA binding protein 6 (GATA6), an epithelial differentiation-related protein, through epigenetic modification, and participates in the transformation of pancreatic ductal adenocarcinoma to a subtype prone to metastasis." (PMID 40028035, 2025). "Furthermore, Chen NM and colleagues found that KRAS signaling was required for EZH2-mediated transcriptional activation of the inflammatory transcription factor nuclear factor of activated T cells 1 (NFATC1) in pancreatic ductal adenocarcinoma cells." (PMID 29335012, 2018). "In addition, tumor-derived exosomal LINC01133 can interact with EZH2 and then promotes H3K27 trimethylation, contributing to pancreatic ductal adenocarcinoma tumor growth and epithelial-mesenchymal transition in vivo." (PMID 34868904, 2021).
Sepsis (15 papers, 2018 to 2026). Sepsis is defined as life-threatening organ dysfunction caused by a dysregulated host response to infection. "In cancer, Ezh2 blockage might induce anti-inflammatory macrophages, resulting in less severe sepsis or more infection susceptibility due to the inadequate inflammation to control organisms." (PMID 37239864, 2023). "Conversely, EZH2 expression is increased in CD4+ T cells and CD14+ monocytes in sepsis, suggesting a disease‐specific role for EZH2 in immune‐mediated conditions." (PMID 41518566, 2026). "EZH2 directly acted on Sox9 to regulate the Wnt/β-catenin pathway and thus affected the apoptosis and inflammatory response during sepsis-induced AKI." (PMID 37064878, 2023). "This study aims to investigate the potential involvement of the histone methyltransferase zeste homolog 2 (EZH2) in sepsis-induced AKI and its impact on apoptosis and inflammation." (PMID 37064878, 2023). "In mice, the deletion of Ezh2 only in myeloid cells in Ezh2 null mice was enough to induce less severe sepsis, similar to the LPS injection model and pneumococcal sepsis model, highlighting the major impact of macrophages in the cytokine production." (PMID 37239864, 2023). "Nevertheless, LPS tolerance is only a subset of the sepsis-induced immune exhaustion and the evaluation of Ezh2 blockage in sepsis is still scarce." (PMID 36982437, 2023). "Despite the higher disease severity of LPS-CLP over CLP alone, Ezh2 null mice still demonstrated less severe sepsis compared with LPS-CLP in control mice, supporting the anti-inflammatory effect of Ezh2 deletion in macrophages." (PMID 37239864, 2023). "To further explore the biological mechanism of EZH2 in sepsis-induced AKI, we used EZH2iKO mice, and knock out efficiency was tested by IHC and western blotting." (PMID 37064878, 2023). "Despite a proof of concept for the translational use of Ezh2 inhibitors in clinical sepsis, more experiments would be interesting." (PMID 37239864, 2023). "Our results clearly correlate cell death-immune crosstalk with the development of AKI and demonstrate that knock-down of EZH2 get involved in sepsis-induced AKI by up-regulating the transcription of Sox9." (PMID 37064878, 2023). "In contrast, the suppression of Ezh2 worsens inflammatory bowel diseases and sepsis-induced muscle cell apoptosis, perhaps through the more effective pro-inflammatory cytokine production after the loss of DNA reading blockage by methylation (H3K27Me)." (PMID 36982437, 2023). "EZH2 was selected as a key shared gene through the PPI network, which was positively linked to several immune-related molecular pathways in both sepsis and NSCLC." (PMID 36552722, 2022). "EZH2 was positively correlated with CD274 (PD-L1) in both sepsis and NSCLC, and the correlation was statistically significant." (PMID 36552722, 2022). "To illustrate the association between EZH2 and the IME, we conducted a study on the correlation between EZH2 and immune cells to explore the role of EZH2 in sepsis and the NSCLC immune landscape." (PMID 36552722, 2022). "Recently, we have also reported that pharmacological inhibition of EZH2 ameliorates the indirect lung injury and inflammation post sepsis through abrogating M1 macrophage polarization." (PMID 34217280, 2021). "In a CLP model of sepsis, H3K27me3, the repressive epigenetic mark induced by EZH2, persists to inhibit IL12 immunity at least 6 weeks after the initial septic insult." (PMID 34163486, 2021). "In clinical studies of sepsis, EZH2 expression increases proportional to disease severity and correlates with poor clinical outcomes." (PMID 34163486, 2021). "The subcellular localization of BRCA1 in sepsis cells in response to sh-EZH2 or overexpressed EZH2 (oe-EZH2) was assessed by western blot analysis." (PMID 31830649, 2020). "Taken together, EZH2 regulated export from the nucleus of BRCA1 in skeletal muscle cells of sepsis via regulating the extent of AKT-1 phosphorylation." (PMID 31830649, 2020).
Sepsis (continued). "lncRNA MALAT1 was noted to regulate the expression and export from the nucleus of BRCA1 by recruiting zeste homolog 2 (EZH2) in skeletal muscle cells of sepsis." (PMID 31830649, 2020). "Collectively, all of the evidence illustrated that lncRNA MALAT1 functioned through recruiting EZH2 in skeletal muscle cells in sepsis." (PMID 31830649, 2020). "In acute inflammatory conditions such as sepsis, EZH2 expression in monocytes is elevated, which may indicate enhancing repair functions to mitigate organ damage." (PMID 41518566, 2026). "Emerging evidence indicates that EZH2 is upregulated in sepsis-induced AKI." (PMID 40989844, 2025). "In EZH2 knockout mice, there is a marked reduction in renal inflammation and macrophage infiltration, demonstrating that the downregulation of EZH2 participates in sepsis-induced AKI by upregulating the transcription of sex determining region Y box9 (Sox9)." (PMID 40989844, 2025). "Targeting the EZH2/Sox9 signaling pathway may offer novel strategies for preventing or ameliorating sepsis-induced AKI." (PMID 40989844, 2025). "In conclusion, an absence of Ezh2 in macrophages resulted in less severe sepsis, and the use of an Ezh2 inhibitor might be beneficial in sepsis." (PMID 37239864, 2023). "In contrast, suppression of Ezh2 might enhance pro-inflammatory genes, including NF-κB, that possibly worsens inflammatory bowel diseases and muscle cell apoptosis in sepsis." (PMID 37239864, 2023). "Although Ezh2 impacts on sepsis are still inconclusive, Ezh2 is one of the upregulated genes in LPS-tolerant macrophages which is improved by the Ezh2 inhibitor (enhanced TNF-α expression) as an interesting control of macrophage through epigenetic manipulation." (PMID 37239864, 2023). "Interestingly, the best survival rate of Ezh2 null mice with CLP and the better survival rate after LPS-CLP of Ezh2 null compared with control mice indicated a possible beneficial impact of Ezh2 blockage in macrophages during sepsis." (PMID 37239864, 2023). "In the current study, we focused on the mechanism of EZH2 in sepsis-induced AKI." (PMID 37064878, 2023). "Finally, the study showed that the EZH2 inhibitor 3-deazaneplanocin A significantly alleviated sepsis-induced AKI." (PMID 37064878, 2023). "Further experiments on the influence of Ezh2 deletion and Ezh2 inhibitors in sepsis are warranted." (PMID 36982437, 2023). "This suggests that EZH2 may function as a cutting-edge therapeutic option in sepsis-induced AKI pathogenesis." (PMID 37064878, 2023). "Additionally, Ezh2 blockage enhances anti-inflammatory Socs3 that inhibits hyperinflammation in sepsis (here and others), multiple sclerosis, and glucose-activated peritoneal fibrosis." (PMID 37239864, 2023). "Numerous previous studies have shown that EZH2 is involved in the regulation of inflammation 41, which may be related to the pathophysiology of sepsis." (PMID 37064878, 2023). "Likewise, the less severe hyper-inflammation and LPS tolerance after a single and double LPS injection, respectively, in Ezh2 null mice over the control mice also support the benefits of interference of Ezh2 during sepsis." (PMID 36982437, 2023). "Despite these various limitations, our data support the influence of Ezh2 in sepsis." (PMID 36982437, 2023). "Likewise, Ezh2 inhibitors have also attenuated sepsis-induced intestinal disorders, multiple sclerosis, and glucose-activated peritoneal fibrosis in previous reports." (PMID 36982437, 2023). "The extended indication of Ezh2 blockage in sepsis, in addition to cancer treatment, might be beneficial." (PMID 36982437, 2023). "Although there was a limited impact on LPS tolerance, these data supported an anti-inflammatory response of Ezh2 null macrophages after a single LPS stimulation that might be useful as an anti-inflammation in sepsis." (PMID 37239864, 2023). "More studies on the use of Ezh2 blockage in sepsis are warranted." (PMID 37239864, 2023).
Sepsis (continued). "Hence, Ezh2 blockage can be conveniently administered in both sepsis immune responses and is also clinically available." (PMID 36982437, 2023). "Nevertheless, we concluded that Ezh2 inhibitors, an available anticancer treatment, might be beneficial in some situations of sepsis." (PMID 37239864, 2023). "Hence, our results are a proof of concept to use clinically available Ezh2 inhibitors in sepsis, especially the blockage of Ezh2 specifically only in macrophages." (PMID 37239864, 2023). "Targeting the EZH2/Sox9 signaling pathway may provide new strategies for preventing or ameliorating sepsis-induced AKI." (PMID 37064878, 2023). "We also compared the IME landscape of sepsis between the EZH2-high and EZH2-low groups." (PMID 36552722, 2022). "We recently reported histone methyltransferase enhancer of zeste homolog 2 (EZH2) as a key epigenetic regulator that contributes to the dysfunction of innate immune responses to sepsis and subsequent lung injury by mediating the imbalance of macrophage polarization." (PMID 34217280, 2021). "A prediction from the lncATLAS website and a RNA-FISH assay in the present study revealed that both lncRNA MALAT1 and EZH2 were located in the nucleus, indicating that lncRNA MALAT1 and EZH2 might interact with each other in skeletal muscle cells in sepsis." (PMID 31830649, 2020). "Furthermore, we detected the expression of BRCA1 in sepsis skeletal muscle cells after the expression of EZH2 was altered by western blot analysis." (PMID 31830649, 2020). "Hence, the impacts of Ezh2 on inflammation and sepsis are still inconclusive." (PMID 36982437, 2023). "The Ezh2-deleted macrophages induced fewer activities (proteomic and secretome analyses) after LPS stimulation compared with the control states, supporting the less severe sepsis in Ezh2 null (Ezhfl/fl; LysM-Crecre/−) over the control (Ezhfl/fl; LysM-Cre−/−) mice." (PMID 37239864, 2023). "Therefore, we verified that the inhibition of EZH2 could regulate the expression of Sox9 by epigenetics to affect sepsis-induced AKI." (PMID 37064878, 2023). "Hence, the current study was designed with the aim of investigating the potential role of lncRNA MALAT1 in the initiation and development of sepsis, and we have demonstrated that lncRNA MALAT1 functions through the EZH2/BRCA1/AKT-1 axis to affect the progression of sepsis." (PMID 31830649, 2020). "However, there are no studies on EZH2 effects during AKI caused by sepsis, thus the potential mechanisms and the precise function of EZH2 in sepsis-induced AKI are unknown." (PMID 37064878, 2023). "The Ezh2 inhibitor was more effective in the CLP model than the CLP after LPS tolerance, perhaps due to the more profound sepsis severity in the latter condition." (PMID 37239864, 2023). "In our study, the level of EZH2 was positively related to macrophages, NK cells, neutrophils, Th1, Th2, Th17, and CD274 (PD-L1) in both NSCLC and sepsis datasets." (PMID 36552722, 2022). "Although both Ezh2 and KDM6A protein expression in MDSCs remains unchanged during sepsis, KDM6A binding at Hotairm1 promoter increases significantly after sepsis induction." (PMID 35185915, 2022). "EZH2 was positively correlated with CD274 (PD-L1) and PDCD1 (PD-1) expression in sepsis, with statistical significance." (PMID 36552722, 2022). "The involvement of EZH2 in the tumor immune microenvironment (TIME) and sepsis immune microenvironment (IME) was assessed by R software." (PMID 36552722, 2022). "Collectively, this investigation suggests a potential mechanism by which circN4bp1 targets macrophage polarization and function in sepsis-induced ARDS by sponging miR-138-5p, thereby promotion of the expression of EZH2." (PMID 35002536, 2021). "Collectively, the expressions of lncRNA MALAT1, BRCA1, and EZH2 were analyzed, with the predictive results obtained indicating that lncRNA MALAT1, BRCA1, and EZH2 are involved in the progression of sepsis." (PMID 31830649, 2020).
Sepsis (continued). "Flow cytometry was used to detect apoptosis of skeletal muscle cells of sepsis, which revealed that sh-MALAT1 + oe-EZH2 + sh-AKT-1 significantly inhibited cell apoptosis as compared with sh-MALAT1 + oe-EZH2." (PMID 31830649, 2020). "In a model of sepsis-induced AKI, inhibition of EZH2 expression could reduce the apoptotic and inflammatory responses of renal TEC, alleviating AKI by mitigating the transcriptional inhibition of SOX9." (PMID 38169402, 2024). "Indeed, the increased expression of Ezh2 and H3K27 is demonstrated in the circulation of patients with sepsis, which is correlated with increased mortality." (PMID 36982437, 2023). "In CLP sepsis mice, those with CLP alone and CLP at 2 days after twice receiving LPS injection, representing sepsis and sepsis after endotoxemia, respectively, symptoms were less severe in Ezh2 null mice, as indicated by survival analysis and other biomarkers." (PMID 37239864, 2023). "To further explore the mechanism of EZH2 action in sepsis-induced AKI, we used sh-EZH2 cells." (PMID 37064878, 2023). "This study revealed the significant role of EZH2 in maintaining the IME and also suggested that NSCLC and SALI share some similarities in pathogenesis and treatment, which inspired us in terms of the prevention and treatment of sepsis." (PMID 36552722, 2022). "We reported that Ezh2 binds at Hotairm1 promoter in MDSCs with no change in binding levels before and during sepsis, but Ezh2 knockdown reduces H3K27me3 levels on Hotairm1 promoter." (PMID 35185915, 2022). "In addition, downregulation of lncRNA MALAT1 and EZH2 induced by ulinastatin confers a protective effect against LPS-induced CMVEC hyperpermeability and apoptosis in sepsis." (PMID 31830649, 2020). "Taken together, lncRNA MALAT1 interacting with EZH2 stimulated AKT-1 phosphorylation and decreased BRCA1 expression, consequently aggravating the progression of sepsis, highlighting a promising therapeutic option for sepsis." (PMID 31830649, 2020). "Notably, Ezh2 reduced chromatin accessibility by adding methyl marks at the tail of histone H3, and the presence of trimethylation of H3K27 (H3K27me3) at promoter regions is mentioned in sepsis." (PMID 37239864, 2023). "Despite the improved sepsis mortality with the previously known hepatic protection of Ezh2 inhibitor, liver enzyme and bacteremia were not different from sepsis in Ezh2 control mice implying a possible hepatoxicity and incomplete Ezh2 blockage of the selected inhibitor (GSK126)." (PMID 37239864, 2023). "Hence, the impacts of Ezh2 in sepsis are still inconclusive, and an exploration of the influence of Ezh2 with LPS tolerance has never been carried out." (PMID 36982437, 2023). "Therefore, circN4bp1 can function as a miR-138-5p sponge for the modulation of macrophage polarization through regulation the expression of EZH2 and may serve as a potential target and/or prognostic marker for ARDS patients following sepsis." (PMID 35002536, 2021). "lncRNA MALAT1 interacting with EZH2 promoted the extent of AKT-1 phosphorylation and decreased BRCA1 expression and export from the nucleus, thus promoting skeletal muscle cell apoptosis and inflammatory responses and ultimately accelerating the progression of sepsis." (PMID 31830649, 2020).